KIDINS220 (kinase D interacting substrate 220)
Diseases named in the same sentence as KIDINS220 in open-access papers (continued):
Sharing a sentence is not in itself a finding about the gene and the disease.
Parkinson disease (1 paper, 2016). A progressive degenerative disorder of the central nervous system characterized by loss of dopamine producing neurons in the substantia nigra and the presence of Lewy bodies in the substantia nigra and locus coeruleus. "For example, a microarray-based expression profiling of dopaminergic neurons isolated from the substantia nigra of Parkinson’s Disease (PD) patients revealed that Kidins220 levels were significantly decreased compared to controls." (PMID 27013979, 2016).
stenosis (1 paper, 2025). "In summary, we report a new LP de novo variant in KIDINS220 associated with aqueduct stenosis that would have likely resulted in SINO syndrome had the pregnancy continued." (PMID 40317787, 2025).
tumor (17 papers, 2003 to 2025). "Importantly, in this type of cancer there is a high prevalence of activating PI3K/AKT/mTOR pathway alterations linked to tumor cell survival and tumorigenesis, again highlighting the possible role of Kidins220 in cell viability through this cascade." (PMID 37542079, 2023). "In this scenario, it was feasible that SNX27 downregulation in Kidins220f/f mice could lead to lysosomal processing of AQP4 in astrocytes, as it occurs with Kidins220 after SNX27 loss in tumour cells." (PMID 34002021, 2021). "Here we demonstrated that miR-4638-5p is a putative tumor suppressor, which suppresses PCa growth, angiogenesis and castration resistance development through regulating Kidins220, VEGFR and PI3K/AKT pathway." (PMID 27329728, 2016). "To further investigate whether PI3K/AKT pathway mediates Kidins220-induced tumor growth and angiogenesis, we knocked down AKT with shRNA." (PMID 27329728, 2016). "As we have demonstrated in vitro and in vivo that Kidins220 promote tumor angiogenesis through activation of PI3K/AKT and VEGF signalling, Kiddins220 may also involved in both neuroendocrine differentiation and angiogenesis of PCa cells." (PMID 27329728, 2016). "We revealed for the first time that miR-4638-5p regulates Kidins220 mRNA by targeted degradation and consequently suppression of VEGF/VEGFR and PI3K/AKT in CRPC cells, and impact on tumor growth and angiogenesis using in vitro and in vivo models." (PMID 27329728, 2016). "In this study, we also showed for the first time that Kidins220 through VEGF and PI3K/AKT signaling regulates both neo-vascularization from endothelial cells and the formation of vasculogenic mimicry of CRPC cells for tumor angiogenesis." (PMID 27329728, 2016).
cancer (11 papers, 2013 to 2025). A tumor composed of atypical neoplastic, often pleomorphic cells that invade other tissues. "XPR1 and KIDINS220 have recently been shown to form a complex that is required for normal regulation phosphate efflux in certain cancer cells." (PMID 37872410, 2024). "The known function of Kidins220 in cancer is to protect cells for survival when they are under stress." (PMID 27329728, 2016). "In both cases, Kidins220 behaves as an oncogene, affecting the ability of cancer cells to survive, proliferate and migrate/metastasize." (PMID 27013979, 2016). "A growing body of evidence points to a direct role of KIDINS220 in cancer." (PMID 37542079, 2023). "Currently, there is growing evidence showing the involvement of Kidins220/ARMS in various cancers." (PMID 30190671, 2018). "In PCa, Kidins220 may activate PI3K/AKT signaling to sustain cancer cell growth under the stress of androgen deprivation and lead to CRPC." (PMID 27329728, 2016). "As expected, compared with the pCDH-vector transfected control cells, AKT-knockdown PC3 and DU145 cells showed reduction in cancer cell growth (P < 0.05 for all) and angiogenesis (P < 0.01 for all) in vitro and in vivo, similar to the phenotype observed upon Kidins220-knockdown." (PMID 27329728, 2016). "As Kidins220 have been reported to activate VEGFR, which play a key role in cancer neo-angiogenesis, we also investigated the role of Kidins220 in PCa angiogenesis." (PMID 27329728, 2016). "What we could suggest from cancer cell migration studies is that in the presence of the BDNF, p75NTR may be activated by TrkB and Kidins220 upon ephrin receptor phosphorylation leading to STAT3 activation and RhoA inhibition." (PMID 30190671, 2018). "Therefore, the observation that Kidins220 regulated angiogenesis in human cancers via activation of VEGF and PI3K/AKT signaling is not surprising, but this has not been investigated before." (PMID 27329728, 2016).
neurodegenerative disease (3 papers, 2016 to 2025). A disorder of the central nervous system characterized by gradual and progressive loss of neural tissue and neurologic function. "Aberrant expressions of KIDINS220 have been associated with various neuropsychiatric and neurodegenerative diseases." (PMID 40317787, 2025). "In addition, some evidence has began to emerge, linking alterations of Kidins220 expression to the onset of various neurodegenerative diseases and neuropsychiatric disorders." (PMID 27013979, 2016).
neurological disease (2 papers, 2021). "Homozygous mutations of KIDINS220/ARMS cause pregnancy terminations in humans, as well as the heterozygous truncation of KIDINS220/ARMS can lead to a neurological disorder named SINO syndrome." (PMID 33763417, 2021).
autosomal dominant disease (1 paper, 2021). Autosomal dominant form of disease. "This is the first time to report that a single site mutation in KIDINS220/ARMS could be transmitted in two generations, which leads to a severe autosomal dominant disease, SINO syndrome." (PMID 33763417, 2021).
heart disease (1 paper, 2021). "Further potentially disease-relevant protein candidates without a known functional relation to hypertrophy, fibrosis or decompensated heart disease were SLTM, HNRNPLL, FIP1L1, RNMT, KRT18 and PUF60 and the downregulated NUDT4, GCAT, KIDINS220 and ARVCF." (PMID 34937869, 2021).
peripheral neuropathy (1 paper, 2025). A disorder affecting the peripheral nervous system. "Herein, we describe the clinical, electrophysiological, histopathological, and genetic features of a novel KIDINS220 sterile alpha motif (SAM) -like domain mutation identified in a Chinese family with HSP accompanied by severe peripheral neuropathy (PN)." (PMID 41164410, 2025).
psychiatric disorder (1 paper, 2021). A disorder characterized by behavioral and/or psychological abnormalities, often accompanied by physical symptoms. "The novel missense variants identified in KIDINS220 gene in schizophrenic patients could be also associated with cerebral ventricular enlargement in these individuals given it is a frequent feature in this psychiatric disorder, a possibility that should be examined." (PMID 34002021, 2021).
KIDINS220 also shares sentences with these, for which no sentence is quoted: Nystagmus (8 papers); sarcoma (4); arthrogryposis (3); neurodevelopmental disorder (2); rhabdomyosarcoma (2); schizophrenia (2); age-related macular degeneration (1); Aqueduct Stenosis (1); asthma (1); autism spectrum disorder (1); basal cell carcinoma (1); Brachycephaly (1); breast carcinoma (1); central neurocytoma (1); cutaneous melanoma (1); developmental delay (1); extramammary Paget disease (1); Failure to thrive (1); ganglioglioma (1); gastric cancer (1); hereditary angioedema (1); Huntington disease (1); learning disabilities (1); metastatic melanoma (1); microcephaly (1); myeloid malignancies (1); paraganglioma (1); pheochromocytoma (1); skin cancer (1); squamous cell carcinoma (1).
A further 1 disease shares a sentence with KIDINS220 in 1 paper.